RFPL3S (RFPL3 antisense)
Synonyms: RFPL3-AS1; RFPL3-AS; NCRNA00005; RFPL3ANT; RFPL3AS
Gene: Long non-coding RNA gene on chromosome 22 (32,359,886 to 32,382,106, reverse strand). Ensembl gene ENSG00000205853.
Diseases named in the same sentence as RFPL3S in open-access papers:
RFPL3S is named in the same sentence as 5 diseases in open-access papers, as found by Europe PMC text mining. Sharing a sentence is not in itself a finding about the gene and the disease. The quoted sentences say what the papers report.
seminoma (1 paper, 2022). A radiosensitive malignant germ cell tumor found in the testis (especially undescended), and extragonadal sites (anterior mediastinum and pineal gland). "This study is the first to discover the use of the expression profile of testis-specific lncRNA RFPL3S in differentiating seminoma from non-seminoma and prognostically predicting TGCT." (PMID 35669771, 2022).
tumor (1 paper, 2022). "At first, we analyzed the expression of RFPL3S in 33 tumors in the TCGA database through the TCGA pan-tumor data in the GEPIA database, and the results showed that RFPL3S was significantly highly expressed in TGCT." (PMID 35669771, 2022).
RFPL3S also shares sentences with these, for which no sentence is quoted: germ cell tumor (1 paper); infection (1); lung carcinoma (1).